MYOC (myocilin)
Diseases named in the same sentence as MYOC in open-access papers (continued):
Sharing a sentence is not in itself a finding about the gene and the disease.
glaucoma (continued). "List of probable glaucoma-causing mutations identified from MYOC exon sequencing in 529 African American POAG subjects and 270 controls." (PMID 22933836, 2012). "This study added a novel mutation to the existing spectrum of MYOC mutations, suggesting that a mutation in MYOC correlated with glaucoma as observed in this family." (PMID 22876119, 2012). "Myocilin mutants are known to cause glaucoma by gain of function, though the exact pathophysiology underlying MYOC mediated glaucoma pathogenesis is yet to be elucidated." (PMID 22736945, 2012). "Soon after its discovery, mutations in the MYOC gene were found to be linked to 3–4% of primary open-angle glaucoma (POAG) and to a large percent (10–30%) to juvenile open-angle glaucoma (JOAG), an early-onset and more severe form of the disease." (PMID 22615763, 2012). "Mutations in the myocilin gene (MYOC) account for 2%–4% of primary open angle glaucoma (POAG) cases." (PMID 22736945, 2012). "This pedigree is the first report with individuals compound heterozygote for the two most common glaucoma-causing MYOC variants." (PMID 23304066, 2012). "MYOC, the major glaucoma gene previously associated with elevated IOP cases, also affects the actin cytoskeletal structure and neurite outgrowth." (PMID 22570627, 2012). "Among these genes, MYOC has been found to harbor the greatest number of glaucoma-causing mutations with over 80 mutations identified in different populations." (PMID 22933836, 2012). "Mutations in the myocilin gene (MYOC) are associated with primary open-angle glaucoma (POAG) in many different populations." (PMID 22933836, 2012). "To date, small deletion accounts for 2.3% of the mutations identified in myocilin and all of them have been marked as glaucoma causing mutations." (PMID 22736945, 2012). "Causative nonsense and missense MYOC mutations have been implicated in glaucoma in both families and populations, but other mutations that change the coding sequence are found in normal individuals." (PMID 22879734, 2012). "All these findings put together reveal the potential involvement of many different genes in the functions leading to the MYOC-linked glaucoma." (PMID 22615763, 2012). "It is interesting to observe that 78% of the genes from this independent gene list were shown to be altered more ≥1.5X in at least one of the four MYOC mutants, an indication of the physiological causative role of MYOC in glaucoma." (PMID 22615763, 2012). "In summary, we have described the first known pedigree containing compound heterozygotes for the two most common glaucoma-causing MYOC mutations, Gln368STOP and Thr377Met." (PMID 23304066, 2012). "Summary odds ratios from the meta-analysis of the association between primary open-angle glaucoma and myocilin polymorphisms." (PMID 23029558, 2012). "Other rare compound heterozygote MYOC variants have been associated with glaucoma of earlier onset than predicted by a single mutation." (PMID 23304066, 2012). "Previous genome-wide analysis in a Drosophila ocular hypertension model identified transcripts with altered regulation and showed induction of the unfolded protein response upon overexpression of transgenic human glaucoma-associated myocilin." (PMID 23029558, 2012). "Among the various myocilin mutations, Pro370Leu (P370L) mutation is responsible for one of the most severe glaucoma phenotypes and Gln368Stop (Q368X) is the most common mutation reported in POAG patients." (PMID 23028669, 2012). "The overall frequency of probable glaucoma-causing mutations in myocilin was lower in our data set of African American POAG subjects compared to prior reported frequencies of 2%–4% in many different populations." (PMID 22933836, 2012). "In this study, a G to A transition at the first base of codon 367 (in exon 3 of MYOC), which resulted in a glycine to arginine amino acid substitution, was identified, suggesting that MYOC is the glaucoma-causing gene in this family." (PMID 21655360, 2011).
glaucoma (continued). "The interaction of multiple variants within MYOC appeared to be an unlikely cause of glaucoma in our cases." (PMID 21552496, 2011). "According to the Myocilin Allele-Specific Glaucoma Phenotype Database, it has been shown that firm genotype–phenotype correlations exist." (PMID 21677793, 2011). "Lys500Arg is of interest given its close proximity to a cryptic peroxisomal-targeting motif that has been implicated in the pathogenesis of MYOC-associated glaucoma." (PMID 21552496, 2011). "In Chinese glaucoma patients or pedigrees, 12 MYOC mutations have been identified, among which Pro370Leu is the most frequently identified variant." (PMID 21677793, 2011). "Here we examined the role of MYOC mutations in a black South African population with primary open-angle glaucoma (POAG)." (PMID 21552496, 2011). "Among these genes, MYOC has been found to harbor more glaucoma-causing mutations than any other identified risk gene." (PMID 21552496, 2011). "The myocilin (MYOC) gene, the first detected causative gene for glaucoma, is located on chromosome 1q23-q24 and encodes a secreted glycoprotein protein." (PMID 21677793, 2011). "Thereby, myocilin P370L mutant would represent, up-to-date, the one that causes the most severe glaucoma phenotype by eliciting the most potent inhibition of the myocilin processing." (PMID 21709622, 2011). "Studies of rare families have mapped the position of 14 POAG genes to small regions of the genome and glaucoma-causing genes have been discovered in two of these loci, myocilin (MYOC) and optineurin (OPTN)." (PMID 21321670, 2011). "A heterozygous missense C→T mutation in exon 3 of MYOC was found in this family, co-segregating with all glaucoma cases." (PMID 21677793, 2011). "Although the G367R mutation of MYOC, which causes primary open-angle glaucoma in the form of autosomal dominant inheritance, has been reported in some other ethnicities, it was found in Chinese pedigree for the first time." (PMID 21655360, 2011). "Myocilin (MYOC) mutations are associated with primary open-angle glaucoma (POAG) in multiple populations." (PMID 21552496, 2011). "In these families, MYOC mutations were found to associate with glaucoma phenotypes characterized by: 1) juvenile or early-age onset (<40 years); 2) high intraocular pressure; and 3) autosomal dominant inheritance." (PMID 21552496, 2011). "Previous genome-wide analysis in a Drosophila ocular hypertension model identified transcripts with altered regulation and showed induction of the unfolded protein response (UPR) upon overexpression of transgenic human glaucoma-associated myocilin (MYOC)." (PMID 21655191, 2011). "This MYOC mRNA stability can be regulated by over-expression of optineurin, another protein associated with glaucoma." (PMID 21709622, 2011). "One American family carrying the p.D380H MYOC mutation presented with an intermediate phenotype between juvenile and adult onset glaucoma." (PMID 20806035, 2010). "Both in vitro and in vivo data strongly indicated that the accumulation of mutant myocilin in the ER of human trabecular meshwork (HTM) cells is one reason for the development of myocilin-associated glaucoma." (PMID 20664690, 2010). "The Q368X mutation is predicted to result in a truncated MYOC-protein and was identified in two families during a screen of four different chromosome 1q-linked glaucoma families and in 3/103 unrelated open angle glaucoma patients." (PMID 19148291, 2009). "The fact that MYOC polymorphisms are implicated in both myopia and glaucoma is intriguing, especially in light of the higher-than-chance co-occurrence of myopia and glaucoma seen in many studies." (PMID 19180258, 2009). "The presence of a P370L mutation of MYOC in all six glaucoma patients suggests a casual association between this mutation and juvenile glaucoma with goniodysgenesis." (PMID 19668597, 2009).
glaucoma (continued). "A French-Canadian family has been described in which both parents had glaucoma due to heterozygosity for the K423E mutation of the MYOC gene." (PMID 19148291, 2009). "The human glaucoma-associated myocilin (MYOC) protein has been associated with congenital glaucoma and with a small percentage of POAG cases." (PMID 19148291, 2009). "MYOC-induced ocular secretion with progressive deterioration of visual function is reminiscent of the pathogenic sequelae that lead to the manifestation of MYOC-associated glaucoma." (PMID 19148291, 2009). "Other transgenic mice in which an Y423H MYOC mutant transgene was introduced displayed symptoms of glaucoma including elevated intraocular pressure and loss of retinal ganglion cells." (PMID 19148291, 2009). "Despite intensive research efforts, however, the precise role of MYOC mutations in glaucoma is unclear." (PMID 19180258, 2009). "Although most MYOC mutations that are associated with glaucoma are missense substitutions, myocilin with these mutations usually manifest phenotypes such as Triton insolubility, formation of intracellular aggregates, and blockage of secretion." (PMID 19287508, 2009). "Nonetheless, the high expression of myocilin in the TMC is easier to reconcile with the role of MYOC polymorphisms in glaucoma than in myopia." (PMID 19180258, 2009). "Targeted expression of human glaucoma-associated MYOC in the Drosophila eye results in a fluid extrusion phenotype reminiscent of ocular hypertension accompanied by visual behavioral impairments." (PMID 19148291, 2009). "The purpose of this study was to examine MYOC for mutations in Japanese patients with primary open-angle glaucoma (POAG) and to determine the phenotypes of the patients with these mutations." (PMID 18334962, 2008). "After initial association of Arg46X and several other variations in MYOC with glaucoma, the causative nucleotide changes were also identified in control individuals." (PMID 18385784, 2008). "Given that approximately 70 glaucoma-associated variations have been identified in MYOC among the many patients screened in the 10 years since the discovery of the gene, finding two novel mutations among only 23 probands is notable." (PMID 18385784, 2008). "Although the mechanism underlying glaucoma is poorly understood, a growing body of evidence suggests that there is a genetic link between MYOC mutations and the pathogenesis of glaucoma." (PMID 18776955, 2008). "The incidence of MYOC mutations in unselected glaucoma patients reportedly ranges between 3%–5% in other populations." (PMID 18449353, 2008). "The present study reveals that the Gln337stop mutation of MYOC is deemed to largely contribute to the early onset glaucoma in this pedigree." (PMID 18776955, 2008). "Ten villagers who were diagnosed with glaucoma had normal MYOC sequences, although one had the Tyr347Tyr polymorphism." (PMID 18449353, 2008). "Based upon the high reported incidence of glaucoma in Taxiarchis and our previous findings of the Thr377Met MYOC mutation in the Greek population, we undertook a community-based study to determine if this variant was present in this village." (PMID 18449353, 2008). "It is also possible that a gene that is responsible for juvenile onset primary open-angle glaucoma can also contribute to adult forms of the disease as has been shown for some mutations in the gene coding for myocilin." (PMID 18648523, 2008). "In the present study, we investigate the pathogenic mechanism by which heterozygous mutations in MYOC cause glaucoma." (PMID 19023451, 2008). "The families in our study also show incomplete penetrance of the Thr377Met MYOC mutation, suggesting that this particular variant is more likely to be a susceptibility factor than a major glaucoma gene." (PMID 18449353, 2008). "The Q368X myocilin mutation represents a particular case in glaucoma pathogenesis since it produces a truncate protein which lacks the COOH-terminal half of the olfactomedin-like domain." (PMID 19023451, 2008).
glaucoma (continued). "A missense mutation (Pro370Leu) in exon 3 of MYOC, one of the candidate genes mapped in this region, was identified in this family to cosegregate with the glaucoma phenotype." (PMID 18728751, 2008). "The incidence of glaucoma and the Thr377Met MYOC mutation in this population is much higher than that reported for other European populations." (PMID 18449353, 2008). "The clinical phenotype of the Thr377Met MYOC variant is intermediate between the more aggressive and severe glaucoma found in patients with the Pro370Leu mutation and the mild presentation of the Glu368Stop mutation." (PMID 18449353, 2008). "Higher incidences of MYOC mutations are found in juvenile glaucoma and mixed-onset primary open-angle glaucoma families (30%–33%)." (PMID 18449353, 2008). "The same behavior was observed with the myocilin mutation, Pro370Leu, which was used as a control because it is associated with one of the most severe myocilin glaucoma phenotypes." (PMID 17615537, 2007). "The aim of this study was to determine if there is a common founder for the Thr377Met myocilin mutation in primary open angle glaucoma (POAG) families with various ethnic backgrounds." (PMID 17417609, 2007). "Allele frequencies of myocilin promoter and coding sequence variations in primary open-angle glaucoma, adult-onset ocular hypertension, and control subjects." (PMID 17615537, 2007). "We have found that heterozygous glaucoma MYOC mutations are located in the olfactomedin-like domain in 2.7% of POAG patients from Southeast Spain in accordance with frequencies reported in other populations." (PMID 17615537, 2007). "Our results imply that the Thr377Met MYOC mutation should be considered in glaucoma patients of Greek descent in particular." (PMID 17417609, 2007). "Both in vitro and in vivo data strongly indicate that the accumulation of mutant myocilin in the ER of HTM cells is necessary for development of myocilin-associated glaucoma." (PMID 17515882, 2007). "This present study provides new insights into the relationship between myocilin-associated glaucoma and the function of the ER and mitochondria." (PMID 17515882, 2007). "Mutations in MYOC have been identified as the cause of primary open-angle glaucoma and the risk factors of different types of glaucoma." (PMID 17438518, 2007). "This approach could offer a durable, safe, and effective solution for patients with MYOC-associated glaucoma and other genetic diseases with further optimization and validation." (PMID 41210166, 2025). "Next, we investigated whether liposomes carrying Cas9 and guide RNA edit MYOC and reduce elevated IOP in this mouse model of MYOC-associated glaucoma." (PMID 41210166, 2025). "The pathogenesis of myocilin-associated glaucoma is associated with a toxic gain of function." (PMID 39726989, 2025). "Previously, we developed a transgenic mouse model (Tg-MYOCY437H) of myocilin POAG by random genomic insertion of the human mutant myocilin and demonstrated that Tg-MYOCY437H mice develop glaucoma phenotypes closely resembling those seen in patients with POAG with the Y437H MYOC mutation." (PMID 39836483, 2025). "Thus, the MYOC variants associated with glaucoma result from a toxic gain of function due to its misfolding." (PMID 40385286, 2025). "This approach could be translated as a precision medicine to treat myocilin-associated glaucoma with in situ antibody expression." (PMID 39726989, 2025). "The Cre/loxP system, a widely utilized genetic tool that enables precise control over gene expression in specific tissues or at designated times, enabled us to specifically target and express the mutant MYOC gene in the TM, the primary disease site in MYOC-associated glaucoma." (PMID 41210166, 2025). "Mutations in the MYOC gene, encoding the extracellular matrix protein myocilin, are the most commonly identified single gene cause of primary open angle glaucoma (POAG) and juvenile open angle glaucoma (JOAG), identified in 2–4% and 10–30% of cases, respectively." (PMID 41011222, 2025).
glaucoma (continued). "Continued analysis of myocilin variants may advance the understanding and treatment of primary open-angle glaucoma." (PMID 40458333, 2025). "The MYOC gene, which encodes for myocilin, was one of the first genes associated with glaucoma." (PMID 39847376, 2025). "Importantly, Cre-induced Tg.CreMYOCY437H mice closely mirror essential features of human MYOC-associated glaucoma, including IOP elevation due to TM dysfunction and glaucomatous neurodegeneration due to sustained IOP elevation." (PMID 41210166, 2025). "An individual with a low PRS could have a high risk of developing glaucoma if they have a strong family history or carry a juvenile onset pathogenic monogenic variant (e.g., in MYOC)." (PMID 39929609, 2025). "The most common MYOC variant (p.Gln368Ter) has a mean age at diagnosis of 52 years with incomplete penetrance, whilst other variants such as p.Pro370Leu or p.Gly367Arg can lead to glaucoma in childhood or early adulthood." (PMID 39929609, 2025). "Taken together, these humanized models have provided crucial platforms for dissecting the pathogenic mechanisms underlying MYOC-associated glaucoma and serve as valuable tools for testing novel therapeutic strategies targeting mutant MYOC-induced ocular hypertension and neurodegeneration." (PMID 41227293, 2025). "Thus, we propose that age-related MYOC somatic mutations are also major contributors to the onset of glaucoma, and the mechanisms driving the emergence of glaucoma have both hereditary and crucial environmental components." (PMID 38397193, 2024). "Importantly, our studies lay the foundation for further development of gene editing methods effectively treat MYOC-associated glaucoma." (PMID 38521856, 2024). "Moreover, S341P mutation of the MYOC gene (MYOCS341P) is associated with a severe pathological glaucoma phenotype in five generations of Chinese families." (PMID 38212635, 2024). "MYOC, the gene that encodes myocilin, is a genetic risk factor for glaucoma." (PMID 38338933, 2024). "Here, we probe the relationship between unfolding and aggregation for glaucoma-associated myocilin." (PMID 38168102, 2024). "Glaucoma-associated OLF variants compromise the thermal stability of MYOC, leading to protein misfolding and a decrease in melting temperature (Tm), thus reducing protein folding efficiency and promoting the formation of aggregates within the endoplasmic reticulum (ER) of TM cells." (PMID 38397193, 2024). "So, the different mutations in MYOC may play diverse roles in the pathogenesis of glaucoma and potential clinical therapy." (PMID 38212635, 2024). "Myocilin-associated glaucoma is transmitted as an autosomal dominant trait." (PMID 39456800, 2024). "MYOC is one of the primary genes associated with primary open-angle glaucoma." (PMID 39766826, 2024). "Similar to the MYOC p.(Cys25Arg) variant, which has been reported as one of the glaucoma-causing variants in the signal peptide sequence, the MYOC p.(Cys5Trp) variant is associated with cysteine residues and may impair normal secretion of myocilin." (PMID 39669598, 2024). "TM cells, particularly sensitive to prolonged ER stress, may eventually perish, thereby contributing to elevated IOP and the development of glaucoma in individuals with MYOC mutations." (PMID 38671671, 2024). "In addition to being a prevalent JOAG-causing mutation, MYOC p.Pro370Leu is associated with severe pathology, and MYOC p.Tyr437His is correlated with the form of glaucoma characterized by an earlier age of onset and significantly elevated IOP levels." (PMID 38671671, 2024). "Since myocilin is not required for IOP regulation and mutant myocilin acquires toxic gain-of-function phenotype leading to TM cell death, knocking out myocilin at the genomic level becomes an attractive strategy for developing a novel therapy for MYOC-associated glaucoma." (PMID 38521856, 2024). "Interestingly, the list of proteins identified in the vitreous-derived EVs included the glaucoma-associated protein myocilin." (PMID 37113676, 2023).